NTNG1 (netrin G1)
Description:
Involved in controlling patterning and neuronal circuit formation at the laminar, cellular, subcellular and synaptic levels. Promotes neurite outgrowth of both axons and dendrites.
Synonyms: KIAA0976; LMNT1; NetG1; NetrinG1
Tractability: Antibody: UniProt places it where antibodies can reach, with high confidence; its Gene Ontology location is reachable by antibodies, with high confidence; UniProt predicts a signal peptide or a membrane-spanning region; the Human Protein Atlas places it where antibodies can reach.
Gene: Protein-coding gene on chromosome 1 (107,140,007 to 107,484,923, forward strand). Ensembl gene ENSG00000162631.
Subcellular location: Cell membrane
Subcellular location (Human Protein Atlas): Plasma membrane
Pathways (Reactome):
Metabolism of proteins: Post-translational modification: synthesis of GPI-anchored proteins
Gene Ontology:
Molecular function: cell adhesion molecule binding; cell-cell adhesion mediator activity; protein binding
Biological process: synaptic membrane adhesion; axonogenesis; regulation of neuron migration; regulation of neuron projection arborization; regulation of neuron projection development; modulation of chemical synaptic transmission
Cellular component: plasma membrane; extracellular region; glutamatergic synapse; presynaptic active zone membrane; Schaffer collateral - CA1 synapse
Genetic constraint (gnomAD): Loss-of-function variants: 16 observed, 54.68 expected, observed/expected ratio (o/e) 0.29, 90% interval 0.2 to 0.44. The upper end of that interval is the gene's LOEUF score, 0.44, which puts it in group 1 of 6, group 1 being the genes least tolerant of losing a copy. Missense variants: 495 observed, 666.64 expected, observed/expected ratio (o/e) 0.74, 90% interval 0.69 to 0.8. Synonymous variants: 244 observed, 261.14 expected, observed/expected ratio (o/e) 0.93, 90% interval 0.84 to 1.04.
Gene-disease validity (ClinGen):
ClinGen rates the evidence that NTNG1 causes each of these diseases.
complex neurodevelopmental disorder (autosomal dominant): Limited. A disorder that involves more than one phenotype associated with the central nervous system, including but not limited to intellectual disability, autism, and seizures (epilepsy).
Homologues: Orthologues: chimpanzee NTNG1 (100% identical), macaque NTNG1 (100% identical), guinea pig NTNG1 (98% identical), rat Ntng1 (98% identical), rabbit NTNG1 (98% identical), pig NTNG1 (97% identical), mouse Ntng1 (96% identical), dog NTNG1 (95% identical), zebrafish ntng1a (71% identical), tropical clawed frog ntng1 (59% identical), zebrafish ntng1b (56% identical). Paralogues in human: NTNG2 (56% identical), LAMA1 (29% identical), LAMA3 (29% identical), LAMB1 (29% identical), LAMC1 (28% identical), LAMA5 (28% identical), LAMA2 (28% identical), LAMB2 (28% identical), LAMB4 (28% identical), LAMC3 (27% identical), NTN1 (25% identical), LAMB3 (24% identical), and 15 more.
Diseases named in the same sentence as NTNG1 in open-access papers:
NTNG1 is named in the same sentence as 57 diseases in open-access papers, as found by Europe PMC text mining. Sharing a sentence is not in itself a finding about the gene and the disease. The quoted sentences say what the papers report.
schizophrenia (14 papers, 2012 to 2023). A major psychotic disorder characterized by abnormalities in the perception or expression of reality. "Genetic variations or disruption of Netrins (NTNG1/2) are also linked to bipolar disorder, schizophrenia and Rett syndrome." (PMID 37941606, 2023). "NTNG1 is associated with neurological diseases, including Rett syndrome, schizophrenia, and bipolar disorder." (PMID 35505885, 2022). "First, we note that other genetic variants in NTNG1 have been associated with schizophrenia risk in people of Japanese, Han Chinese, and European ancestry." (PMID 34073619, 2021). "Previous studies revealed that mutations in NTNG1 are associated with schizophrenia and Parkinson’s disease." (PMID 27483138, 2016). "The susceptibility genes (such as DISC1, RELN, GABA, SHANK3, NRXN1, NTNG1, etc.), which were associated with schizophrenia, also confer risk to ASD." (PMID 26204268, 2015). "Disruption of Cntn4 is known to cause developmental delay and mental retardation, as well as autism, while Ntng1 mutations are a cause of Rett syndrome and have been implicated in the pathophysiology of schizophrenia." (PMID 23251410, 2012). "NDST3 and NTNG1 were both found to be highly associated with schizophrenia in humans." (PMID 36980855, 2023). "Studies on the correlation of gene polymorphisms in schizophrenia revealed that NTNG1 and its paralogues for NTNG2 gene may be related to the pathophysiology of schizophrenia." (PMID 34814929, 2021). "NTNG1 and NTNG2 are associated with schizophrenia and bidirectional affective disorder." (PMID 32251318, 2020). "For instance, netrin-G1 is associated with Rett syndrome, ASD, schizophrenia and bipolar disorder." (PMID 31680855, 2019). "In addition, netrin-G1 and CDKL5, known to bind NGL-1, have been implicated in various brain disorders—netrin-G1 with Rett syndrome, ASD, schizophrenia and bipolar disorder, and CDKL5 with Rett syndrome, epilepsy, intellectual disability, and ASD." (PMID 31680855, 2019).
Rett syndrome (11 papers, 2012 to 2023). A severe neurodevelopmental disorder affecting the central nervous system. "Reports indicate that NTNG1 is a causative gene of the atypical Rett syndrome, since CDKL5 has historically been considered causative gene of the atypical Rett syndrome, suggesting that NGL-1 is one of the physiological substrates of CDKL5." (PMID 32587608, 2020). "Mutations in the NTNG1 gene are linked to Rett syndrome with epileptic seizures of early onset, and a more recent study revealed that netrin G2 dysfunction is associated with a Rett-like phenotype with areflexia." (PMID 33520982, 2020). "Furthermore, Netrin-G1 (NTNG1) disruptions or polymorphisms have been associated with atypical Rett syndrome, intellectual disability, autism spectrum disorder, and schizophrenia." (PMID 30410030, 2018). "The disruption of the NTNG1 gene from chromosome 1 abnormal rearrangement was detected in a female patient with Rett syndrome, a progressive neurodevelopmental disorder once characterized as a type of ASD." (PMID 34947998, 2021). "Single nucleotide polymorphisms or abnormal expression of NTNG1 and NTNG2 are related to psychiatric disorders such as autism, Rett syndrome, schizophrenia, and bipolar disorder in human and murine models." (PMID 33520982, 2020).
autism (6 papers, 2012 to 2023). Persistent deficits in social interaction and communication and interaction as well as a markedly restricted repertoire of activity and interest as well as repetitive patterns of behavior. "In addition, mutation of Ntng1 has been suggested as a causative factor for Rett syndrome-like disorders in patients, such as intellectual disability, epilepsy, and autism." (PMID 34819847, 2021). "Developmental regression, autism, and epilepsy can also be seen in disorders of ion channels (i.e., Dravet syndrome), impairments of receptor expression (i.e., GRIN1), transcription factors (i.e., MEF2C), axonal guidance (i.e., NTNG1), and ubiquination (i.e., RHOBTB2)." (PMID 37511662, 2023).
Anxiety (5 papers, 2016 to 2023). Intense feelings of nervousness, tension, or panic often arise in response to interpersonal stresses. "Netrin-G1 is a glycosyl-phosphatidylinositol-anchored synaptic adhesion molecule whose deficiency results in impaired fear-like and anxiety-like behaviors under specific circumstances." (PMID 27345935, 2016). "Genetic deletion of netrin-G1 in cortical excitatory neurons resulted in altered anxiety-like behavior, but intact fear-like behavior, whereas loss of netrin-G1 in inhibitory neurons resulted in attenuated fear-like behavior, but intact anxiety-like behavior." (PMID 27345935, 2016). "Moreover, NTNG1 deficiency contributed to fear-like and anxiety-like behavioral disturbances." (PMID 36834894, 2023). "Netrin-G1 knockout mice show anxiety behaviors in the elevated plus-maze test and exhibited deficits in fear response behavior." (PMID 34947998, 2021). "We demonstrated that ablation of netrin-G1 in cortical excitatory neurons selectively alters anxiety-like behavior while ablation of netrin-G1 in inhibitory neurons alters fear-like behavior." (PMID 27345935, 2016). "For anxiety evaluation tasks, it is especially interesting that netrin-G1 KO mice demonstrated reduced anxiety in the EPM test, but not the OF test, whereas netrin-G2 KO mice exhibited abnormalities in both tests." (PMID 26746425, 2016). "The fear-conditioning task was solely influenced by netrin-G1, while anxiety appeared to be regulated by both genes." (PMID 26746425, 2016). "The reasons for the differential anxiety-related behaviors of netrin-G1 KO mice are unclear." (PMID 26746425, 2016). "Further virus-mediated cell-specific genetic studies (including local deletion and rescue experiments) may help to identify the precise neural circuits through which netrin-G1 regulates fear and anxiety-like behavior." (PMID 27345935, 2016). "In addition, netrin-G1 global KO (gKO) mice exhibit marked alterations in fear-like and anxiety-like behaviors under specific circumstance." (PMID 27345935, 2016). "To investigate the mechanisms responsible for the emotion-related behavioral deficits observed in netrin-G1 gKO mice, we created mice with Cre-mediated conditional deletions of the netrin-G1 gene in defined cell types of the brain and examined fear-like and anxiety-like behavioral phenotypes." (PMID 27345935, 2016). "Emx1-G1-cKO mice, however, exhibited no preference for the closed arms (open arms: 39.3 ± 5.0%; closed arms: 41.3 ± 5.6%), indicating less anxiety-like behavior in the EPM, similar to netrin-G1 gKO mice." (PMID 27345935, 2016). "In this study, we demonstrated that anxiety-like behavior in the EPM and the conditioning stage of FC test triggered differential induction patterns of an immediate-early gene in netrin-G1 gKO mice." (PMID 27345935, 2016). "As netrin-G1 is not expressed in CA3 cells, and CA3 mainly receives inputs from the entorhinal cortex and DG where netrin-G1 is strongly expressed, it is possible that the netrin-G1-positive cells in the entorhinal cortex and/or DG are mainly responsible for regulating anxiety-like behavior." (PMID 27345935, 2016).
bipolar disorder (5 papers, 2019 to 2023). A disorder of the brain that causes unusual shifts in mood, energy, activity levels and the ability to carry out day-to-day tasks. "The levels of NTNG1 mRNA, especially isoform G1c, and NTNG2 are decreased in patients with bipolar disorder." (PMID 33520982, 2020).
pancreatic cancer (5 papers, 2020 to 2024). "NTNG1 mutation has also been associated with poor prognosis in colorectal and pancreatic cancer." (PMID 36045381, 2022). "The uptake of these Netrin-G1 + CAF-derived exosomes by pancreatic cancer cells activates the PI3K/Akt signaling pathway, reducing apoptosis in conditions of nutrient deficiency, thus facilitating cancer cell survival and growth under adverse conditions." (PMID 38954230, 2024). "Moreover, a distinct subset of CAFs characterized by the expression of Netrin-G1 has been shown to produce unique exosomes that support the survival and adaptation of pancreatic cancer cells under nutritional stress." (PMID 38954230, 2024). "Further investigation revealed that a lack of Netrin G1 in fibroblasts or lack of NGL1 in pancreatic cancer cells severely affected the ability of the latter to survive upon nutrient starvation." (PMID 33088423, 2020). "Moreover, it is demonstrated that as regulator of glutamate, glutamine, and cytokine release, Netrin G1 (NetG1) in CAFs and Netrin G1 Ligand (NGL-1) in pancreatic cancer cells enhanced tumorigenesis by allowing cancer cells to survive in low nutrient conditions and reduced death induced by NK cells." (PMID 34976805, 2021).
epilepsy (4 papers, 2019 to 2023). A brain disorder characterized by episodes of abnormally increased neuronal discharge resulting in transient episodes of sensory or motor neurological dysfunction, or psychic dysfunction. "Two patients harboring Netrin G1 (NTNG1) variants were described with atypical RTT (regression, hand apraxia, dyspraxic gait and HS, and unspecified epilepsy since 6 years of age) and with an RTT-like phenotype, respectively." (PMID 34440332, 2021).
ovarian carcinoma (3 papers, 2021 to 2024). A malignant neoplasm originating from the surface ovarian epithelium. "Clinicopathological characteristics and their associations with the expression level of NTNG1 in ovarian cancer tissues." (PMID 34277602, 2021). "NTNG1 belongs to the family of netrins, with an elevated level of NTNG1 reported to result in cisplatin resistance in ovarian cancer." (PMID 36045381, 2022). "Overall, the level of NTNG1 was higher in cisplatin-resistant ovarian cancer tissues compared with cisplatin-sensitive ones; patients with a high NTNG1 level in cancer tissues had shorter PFS and PFI." (PMID 34277602, 2021). "Bioinformatic analyses of the GSE45553 and GSE73935 datasets indicated that NTNG1 was a candidate gene involved in cisplatin resistance in ovarian cancer; the BioGRID demonstrated an interaction between NTNG1 and GAS6." (PMID 34277602, 2021). "Here, the correlation between the expression level of NTNG1 and cisplatin response in ovarian cancer was evaluated using online datasets, and the role of NTNG1 in cisplatin resistance was explored with knock-in and knockdown experiments." (PMID 34277602, 2021). "The KM plotter indicated that a higher expression level of the NTNG1 gene was related to a shorter PFS of ovarian cancer patients in overall as well as in the subgroup that received cisplatin treatments (p = 0.005, p < 0.001)." (PMID 34277602, 2021). "As a result, NTNG1 was identified as a potential therapeutic target for ovarian cancer, and blocking NTNG1 might be a viable method for overcoming cisplatin resistance." (PMID 38546656, 2024). "Thus, NTNG1 was a target for ovarian cancer treatment, and inhibiting NTNG1 may be a useful strategy to overcome cisplatin resistance." (PMID 34277602, 2021). "However, the role of NTNG1 in ovarian cancer remains unclear." (PMID 34277602, 2021). "Preliminary data indicated that NTNG1 bound GAS6/AXL to activate the Akt pathway, thereby modulating the response of ovarian cancer cells to cisplatin." (PMID 34277602, 2021). "Cisplatin induced an increase in the level of p-AXL and p-Akt, confirming their roles in cisplatin resistance of ovarian cancer cells; the inductive effect was amplified in SKOV3 cells following overexpression of NTNG1, and an opposite result was observed in SKOV3/DDP cells when silencing NTNG1." (PMID 34277602, 2021).
Anorexia (2 papers, 2012 to 2016). Lack of desire to eat (loss of appetite). "Variants of human NTNG1 have been suggestively associated with anorexia, while the orthologous rat gene is encompassed within four QTLs for cardiac mass and several others for body and organ weight." (PMID 22859963, 2012).
breast carcinoma (2 papers, 2020 to 2022).
cerebral atherosclerosis (2 papers, 2021 to 2023). Atherosclerosis of the cerebral vasculature. "In conclusion, we identified a novel risk locus in NTNG1 that may contribute to cerebral atherosclerosis severity by mediating brain protein levels of CNOT3, a sub-unit of the master regulator CCR4−NOT." (PMID 34073619, 2021). "To explore potential mechanisms for the two lead SNPs that were associated with cerebral atherosclerosis from the meta-analysis of the community-based studies, we tested whether they were associated with RNA and protein expression of NTNG1, the gene in which they are located." (PMID 34073619, 2021). "A novel locus of NTNG1 has been found in patients with cerebral atherosclerosis." (PMID 37662558, 2023).
Restless Leg Syndrome (2 papers, 2017 to 2020). "Sleep end is also associated with one SNP at gene NTNG1 related to Restless Leg Syndrome and BMI, one SNP near LINC00963, and one SNP near GLRX3." (PMID 33075057, 2020). "The BI-ENRICH algorithm showed that most of the top pathways identified for restless legs syndrome were related to neurodevelopment, including neurogenesis (genes MDGA1, MYT1, NTNG1, and SEMA6D), cell-junction organisation (PKP4 and SMAD3), and axon guidance (NTNG1 and SEMA6D)." (PMID 29029846, 2017).
age (1 paper, 2024). A temporal measurement of the time period elapsed since an identifiable point in the life cycle of an organism. "Downregulation of Ntng1 and Lrrtm3 might affect hippocampal glutamatergic synapses and contribute to age‐related cognitive impairment, which is consistent with our functional analysis results." (PMID 39468399, 2024).
AIDS (1 paper, 2020). A syndrome resulting from the acquired deficiency of cellular immunity caused by the human immunodeficiency virus (HIV). "Of these, 186 (74.4%) NTNG1 eQTLs were associated with AIDS and 57 (22.9%) were associated with non-obstructive azoospermia." (PMID 32251318, 2020).
anorexia nervosa (1 paper, 2016). A disorder most often seen in adolescent females characterized by a refusal to maintain a minimally normal body weight, an intense fear of gaining weight, a disturbance in body image, and, in postmenarcheal females, the development of amenorrhea. "Of those nine genes, AKAP6 and NTNG1 were genes associated with anorexia nervosa and the remaining seven (AGT, CD36, CD38, FOXP1, PPARA, PPARG and SELL) were selected for their relationship with T2D." (PMID 27483138, 2016). "A total of eleven of genes were differently expressed in celiac patients compared with disease controls of which CD36, CD38, FOXP1, SELL, PPARA, PPARG, AGT previously associated with type 2 diabetes and AKAP6, NTNG1 with anorexia nervosa remained significant after correction for multiple testing." (PMID 27483138, 2016). "AKAP6 and NTNG1 were previously reported in a GWAS of anorexia nervosa." (PMID 27483138, 2016).
autoimmune disease (1 paper, 2025). A disorder resulting from loss of function or tissue destruction of an organ or multiple organs, arising from humoral or cellular immune responses of the individual to their own tissue constituents. "Interestingly, the TGFBR3, THSD7A, and NTNG1 MNTAgs also exhibit podocyte preference expression, supporting the important pathological contributions of podocyte injury to the kidney-limited autoimmune disease of MN." (PMID 40149392, 2025).
Autoimmunity (1 paper, 2025). The occurrence of an immune reaction against the organism's own cells or tissues. "The podocyte-focused expression of PLA2R1, NTNG1, HTRA1, and NDNF is intriguing, highlighting antigen-initiated autoimmunity as causing podocyte injury and the subsequent MN pathogenesis." (PMID 40149392, 2025).
colon cancer (1 paper, 2022). "Results of qPCR suggested that the levels of GJB6 were distinguished according to the status of KRAS-mutation, though we didn’t detect the signals of NTNG1 in colon cancer cell lines." (PMID 35774610, 2022).
colorectal cancer (1 paper, 2021). A primary or metastatic malignant neoplasm that affects the colon or rectum. "It has been shown that abnormal expression of the NTNG1 gene plays a role in the occurrence and recurrence of colorectal cancer, and that an alteration in NTNG1 activity is related to poor prognosis via disruption of the extracellular matrix." (PMID 34277602, 2021).